SLC1A5 (solute carrier family 1 member 5)
Diseases named in the same sentence as SLC1A5 in open-access papers (continued):
Sharing a sentence is not in itself a finding about the gene and the disease.
Parkinson disease (1 paper, 2023). A progressive degenerative disorder of the central nervous system characterized by loss of dopamine producing neurons in the substantia nigra and the presence of Lewy bodies in the substantia nigra and locus coeruleus. "SLC1A5 is a Rho GTPase effector involved in glutamine intake and ferroptosis, with important implications for cancer cell metabolism and neurological disorders, such as Parkinson’s disease." (PMID 36675105, 2023).
renal carcinoma (1 paper, 2022). A carcinoma arising from the epithelium of the renal parenchyma or the renal pelvis. "The inactivation of VHL leads to the structural activation of VEGF and PDGF, which can target downstream glutamine transporter SLC1A5, promotes the metabolic reprogramming of VHL deficient renal cancer cells, selectively reduces the growth and survival of VHL deficient renal cancer cells." (PMID 35022030, 2022).
Sepsis (1 paper, 2025). Sepsis is defined as life-threatening organ dysfunction caused by a dysregulated host response to infection. "In addition to these alternative metabolic routes, specific glutamine transporters such as SLC1A5 (ASCT2) and SLC7A5 (LAT1) play crucial roles in glutamine uptake and metabolic reprogramming in both cancer and sepsis." (PMID 40563999, 2025).
thymic carcinoma (1 paper, 2024). Thymic carcinoma (TC) is a type of thymic epithelial neoplasm characterized by a high malignant potential. "For thymic carcinoma, the novel biomarkers of MSLN, CCL20, and SLC1A5 are identified and observed an elevated expression of LAG3 and HAVCR2 in malignant tumorn‐infiltrating mature T cells." (PMID 39258580, 2024).
cancer (379 papers, 2013 to 2026). A tumor composed of atypical neoplastic, often pleomorphic cells that invade other tissues. "Several glutamine transporters have been confirmed to be widely upregulated in cancer and are associated with tumor invasion and metastasis, such as SLC1A5 (ASCT2), SLC7A5 (LAT1), and SLC6A14." (PMID 41040664, 2025). "For metabolic reprogramming in cancer, a SLC1A5 variant functions as a mitochondrial glutamine transporter." (PMID 40278313, 2025). "A specific SLC1A5 variant has been identified as a mitochondrial glutamine transporter critical for driving cancer metabolic reprogramming." (PMID 41212437, 2025). "Increased SLC1A5 expression has been associated with poor survival in several human cancers, including breast cancer and lung cancer." (PMID 40552664, 2025). "Decreased level of circulating amino acids is linked to increased uptake by cancer cells due to overexpression of amino acid transporters, including SLC1A5 (Gln uptake), SLC1A4 (Ser uptake), SLC7A5 (Leu, Ile, and Val uptake), or SLC7A1 (Arg uptake)." (PMID 38646441, 2024). "Specifically, in the functional coupling between SLC7A5 and SLC1A5, glutamine enters cancer cells through SLC1A5, which then effluxes out of the cells via SLC7A5, linked to the entry of leucine." (PMID 38459595, 2024). "The series of hydroxyproline analogs identified here represent promising new agents to pharmacologically modulate SLC1A4 and SLC1A5 amino acid exchangers which are implicated in numerous pathophysiological processes such as cancer and neurological diseases." (PMID 38792190, 2024). "SLC1A5, which encodes for the ASCT2 protein, is a sodium-dependent neutral amino acid transporter that plays a role in cellular glutamine homeostasis and is a critical regulator for cancer development and tumor growth." (PMID 39695878, 2024). "A growing number of studies report that high SLC1A5 expression is associated with poor prognosis in cancer." (PMID 38410123, 2024). "ASCT2 (encoded by SLC1A5) is one of the important glutamine transporters which has been reported to transport glutamine and promote cancer cell proliferation." (PMID 39272886, 2024). "In many cancers, the expression of SLC1A5 increases to meet the heightened demand for glutamine caused by rapid cell proliferation." (PMID 39958609, 2024). "Our results indicated that SLC1A5 is aberrantly expressed in most cancer types and closely associated with prognosis." (PMID 37566748, 2023). "Glutamine transport from cytoplasm into the mitochondria is mediated by a recently identified variant of SLC1A5 (SLC1A5_var), transcribed from an alternative transcription initiation site, which plays a critical role in cancer metabolic reprogramming." (PMID 36768660, 2023). "The analysis results for OS, DSS, DFI, and PFI showed that SLC1A5 is closely related to the prognosis of cancer patients and is a risk factor for most cancer types." (PMID 37566748, 2023). "Previous studies also suggested that SLC1A5 overexpression is significantly associated with poor OS in more than half of cancer types, including LGG and GBM." (PMID 37566748, 2023). "Further investigation confirmed that CAIX associates and co-localizes with SLC1A5 in cancer cells, and functions to maintain redox homeostasis through the GSH/GPX4 axis." (PMID 38099193, 2023). "The DFI and PFI results were also examined to fully demonstrate that SLC1A5 is a risk factor for most cancer types and is significantly associated with the prognosis of cancer patients." (PMID 37566748, 2023). "Since OS patient outcomes include noncancer mortality events, we used DSS to evaluate the association between SLC1A5 and patient cancer survival time." (PMID 37566748, 2023). "SLC1A5 variant (SLC1A5_var) is identified as a mitochondrial glutamine transporter in cancer cells recently." (PMID 36351889, 2022). "Researchers have demonstrated that a variant of SLC1A5 is a mitochondrial glutamine transporter that has a critical role in metabolic reprogramming in cancer cells." (PMID 35757505, 2022).
cancer (continued). "The SLC1A5 mRNA concentrations in different tumors and normal tissues linked to multiple cancer types were analyzed in Oncomine." (PMID 34367941, 2021). "SLC1A5, another hit target from our analysis, is a neutral amino acid transporter in which its high expression has been implicated in many cancer types including GBM." (PMID 34301218, 2021). "Of the several transporters that can mediate glutamine uptake across the cellular membrane, ASCT2 (encoded by gene SLC1A5) seems to play a key role in various cancers." (PMID 34203535, 2021). "Consistently, knockdown of the mitochondrial variant of SLC1A5 variant in cancer cells leads to drastic tumor inhibition in vivo." (PMID 33953707, 2021). "Altogether, developing inhibitors that target nutrient transporters, including the mitochondrial SLC1A5 variant, is a promising new approach to weaken the cancer cell metabolism and reduce tumor growth." (PMID 33953707, 2021). "To understand better the relevance and underlying mechanisms of SLC1A5 expression in cancers, we assessed the relation between SLC1A5 expression and the clinical characteristics of HCC patients in the Kaplan-Meier plotter database." (PMID 34367941, 2021). "SLC1A5 is a neutral amino acid transporter that has been associated with greatly enhanced expression levels in stem cells and cancer cells to meet increased glutamine demand." (PMID 34414225, 2021). "Elevated SLC1A5 expression has been linked to poor survival in many human cancers, including those of the liver, lung, breast, colon, and head and neck squamous." (PMID 34367941, 2021). "The alanine-serine-cysteine transporter, type-2 (ASCT2, encoded by gene SLC1A5), is a sodium-dependent solute carrier protein responsible for the import of neutral amino acids and is the primary transporter of glutamine in cancer cells." (PMID 33016874, 2020). "Further studies showed that the loss of function of the SLC1A5 carrier results in cell growth inhibition, autophagy, and apoptosis triggering in solid and hematopoietic malignancies." (PMID 32825551, 2020). "For this second group of cancers, SLC1A5 antagonists or inactivating mutations of SLC1A5 alone are insufficient to stop growth." (PMID 28553292, 2017). "IL-γ-glutamyl-p-nitroanilide has been shown to inhibit SLC1A5 (ASCT2) and cause autophagy in cancer cells." (PMID 27825361, 2016). "Recent research has identified a mitochondrial variant of SLC1A5 that is critical for transporting glutamine into mitochondria, especially under hypoxic conditions, further supporting metabolic flexibility and adaptation in cancer cells." (PMID 40563999, 2025). "Notably, under conditions of serine deprivation, loss of SLC1A5 (ASCT2) has been shown to inhibit cancer cell growth." (PMID 40660426, 2025). "SLC1A5 has been found to be associated with eight types of tumor immune-infiltrating cells and immune state, suggesting that it can be used as a pharmacological target for the development of novel anti-cancer drugs." (PMID 38410123, 2024). "Then, we evaluated the association of SLC1A5 with the prognosis of cancer patients." (PMID 37566748, 2023). "SLC1A5 variant is a mitochondrial glutamine transporter for cancer metabolic reprogramming." (PMID 37365670, 2023). "However, limited information is available regarding the association between SLC1A5 and patient prognosis in cancer." (PMID 37566748, 2023). "Furthermore, the metabolic reprogramming of cancer cells is directly regulated by a mitochondrial variant of SLC1A5." (PMID 37161350, 2023). "In comparison with GPNA, V-9032 has approximately 100-fold increased potency in blocking cellular glutamine uptake, and inhibition of SLC1A5 with V-9032 was demonstrated to cause cell death, disrupt redox equilibrium, and result in disrupted development and progression of cancer." (PMID 36499623, 2022). "Also, a variant of SLC1A5, called SLC1A5_var, promotes metabolic switch by augmenting Gln metabolism in cancer cells." (PMID 33401748, 2021).
cancer (continued). "Although there exist some variations in different types of cancer, which might be caused by the different data collection criteria used in each study and underlying causative mechanisms, SLC1A5 generally is upregulated in cancers." (PMID 34367941, 2021). "Besides, a recently reported novel splice variant of SLC1A5 is a mitochondrial glutamine transporter, which is critical for metabolic reprogramming of cancer cells, thus supporting carcinogenesis." (PMID 34367941, 2021). "Cancer and immune cells import glutamine via solute-linked carrier family 1 member A5 (SLC1A5)." (PMID 32993179, 2020). "Importantly, gene silencing of SLC1A5 or its pharmacological inhibition reverted the resistant phenotype, thereby suggesting that SLC1A5 could be a promising diagnostic marker as well as a therapeutic target for TKI resistant cancers." (PMID 39431017, 2024). "In addition, a study underlying SLC1A5 overexpression demonstrated that cancer energetics as well as cell growth and survival might be modulated in a glutamine-dependent manner." (PMID 36499136, 2022). "Exposure of cancer cells to senescent CM increases Gln uptake, together with upregulation of the transporter SLC1A5 and increased intracellular Gln." (PMID 42121871, 2026). "SLC1A5 is the primary glutamine transporter in cancer cells and has an important role in maintaining the growth and survival of glutamine-dependent cancers." (PMID 40532011, 2025). "Among these, SLC1A5 (also known as ASCT2), SLC7A5 (LAT1) and its heavy chain SLC3A2 (CD98hc), and SLC38A1 (SNAT1) are highly expressed in various cancers and have been implicated in tumor progression, therapeutic resistance and clinical outcome." (PMID 40707944, 2025). "These antibodies successfully recognized SLC1A5 surface domains and inhibited the proliferation of Gln-dependent cancer cells." (PMID 40830338, 2025). "We further demonstrate that c‐Myc–IRP2–IRE axis is responsible for the upregulation of RTN4IP1, and identify SLC1A5, SLC3A2, and SLC7A5, three amino acid transporters implicated in cancer, as essential downstream effectors of RTN4IP1 in ESCC." (PMID 39757767, 2025). "The administration of V-9302, an inhibitor of SLC1A5 that reduces Gln availability, increases glucose uptake in cancer and immune cells in allograft models." (PMID 40723225, 2025). "SLC1A5 is a sodium‐dependent solute carrier protein that imports neutral amino acids and serves as the primary transporter of glutamine in cancer cells." (PMID 40552664, 2025). "Various primary transporters, including B0AT1(SLC6A19), LAT1 (SLC7A5), SNAT5 (SLC38A5), and ASCT2 (SLC1A5), play significant roles in glutamine uptake by cancer cells." (PMID 40223274, 2025). "SLC1A5, the primary transporter responsible for Gln uptake into rapidly proliferating cells (including cancer cells), is a promising target." (PMID 40830338, 2025). "V9302 was originally developed as a potent small-molecule inhibitor of the glutamine transporter ASCT2 (SLC1A5) in mammalian cells, where it was shown to block glutamine uptake and suppress cancer cell growth in preclinical models." (PMID 41148680, 2025). "We now show that ABCG2 regulates SLC1A5-mediated glutamine transport, accompanied by rewiring of cancer cell metabolism, enhanced autophagy, and increased tumor cell survival under stress conditions." (PMID 38641063, 2024). "The alanine-serine-cysteine-transporter-2 (ASCT2 or SLC1A5) mediates the uptake of these glutamines into the cancer cells, and it has been noted that LC patients express these transporters with greater frequency." (PMID 38785748, 2024). "As a therapeutic method, starving cancer cells of glutamine by SLC1A5 inhibitors leads to impairment of tumor progression." (PMID 38705513, 2024). "A significant inhibitory effect of REVs and SLC1A5-OE-EVs was observed on the sensitivity of HCT116 (Colon cancer cell line) cells to 5-FU and on vemurafenib sensitivity of A375 cells." (PMID 39431017, 2024).
cancer (continued). "Solute carrier family 1 member 5 (SLC1A5), a member of the glutamine transporter family, facilitates the uptake of glutamine into cancer cells." (PMID 39440055, 2024). "For example, elevated expression of SLC1A5 and SLC7A5 which regulate the transport of trp was obviously associated with the poor prognosis of several cancers, including lung, kidney, skin and breast cancers." (PMID 39648156, 2024). "Glutamine is transported into cells through plasma membrane transporters (e.g., SLC1A5) and is subsequently converted to glutamate by glutaminase to fuel cancer cell growth." (PMID 38830868, 2024). "In the present study we show that, in addition to its chemoprotective role in cancer cells, ABCG2 can regulate cancer cell metabolism via regulation of the glutamine transporter SLC1A5, resulting in increased glutaminolysis and enhanced redox regulation." (PMID 38641063, 2024). "SLC1A5 plays a significant role in cancer cell metabolism, development, and propagation, and has received attention as a pharmacological target to block cancer cell development and survival." (PMID 39648156, 2024). "SLC1A5 is a crucial sodium-dependent solute carrier protein that facilitates the import of glutamine and serves as the principal conduit through which cancer cells acquire glutamine." (PMID 38459595, 2024). "SLC1A5 promotes the transport of glutamine leucine and Trp in cancer cells and controlled by mTORC1 and MYC signalling pathway." (PMID 39648156, 2024). "The involvement of this SLC1A5-glutamine axis also supports the development of therapeutic interventions against this preferentially upregulated pathway in cancer and in this regard SLC1A5 and glutaminase inhibitors are already in experimental development." (PMID 39431017, 2024). "SLC1A5 is a member of the solute family of membrane bound transporters and is expressed in cancer cells where it facilitates influx of glutamine to supply proliferative cells with the required bioenergetic substrates for metabolic and signalling functions." (PMID 39431017, 2024). "It was previously established that SLC1A5 plays a very important role as a glutamine transporter in cancer cell metabolism 16,17." (PMID 39431017, 2024). "Although inhibiting SLC1A5 in cancer is therapeutically useful, SLC1A5 is expressed in normal tissues which makes SLC1A5 targeting in cancer therapy very challenging." (PMID 38705513, 2024). "Solute carrier family 1 member 5 (SLC1A5) is a transporter of mitochondrial glutamine for cancer metabolic reprogramming." (PMID 38410123, 2024). "Here, we characterize the amino acid transporter ASCT2 (SLC1A5) as a major contributor to serine uptake in cancer cells." (PMID 39068660, 2024). "As such, SLC1A5 has been studied in various cancer types, its upregulation having been observed in various cancers." (PMID 39062801, 2024). "SLC1A5 is the primary transporter for the conditionally essential amino acid glutamine; knockdown of SLC1A5 was shown to result in a 60% decrease in glutamine uptake in some cancer cells." (PMID 38641063, 2024). "In general, cancer cells exhibit enhanced glutaminolysis and glutamine uptake via membrane transporters like SLC1A5 and SLC7A5." (PMID 37887398, 2023). "Our results demonstrate that SLC1A5 can predict the efficacy of ICIs in the treatment of various cancers." (PMID 37566748, 2023). "Among the many amino acid transporters so far identified, SLC7A5 (LAT1) and SLC1A5 (ASCT2) are frequently overexpressed in cancer cells." (PMID 36599897, 2023). "It was reported that SLC1A5, a high-affinity cell membrane transporter for glutamine, was highly expressed in various types of cancer cells including AML cell lines MOLM-14, MV4-11, OCI-AML3, and HL-60." (PMID 37249801, 2023). "To first acquire basic information on SLC1A5 in cancer, we examined the distribution and expression level of SLC1A5 in tumors and normal tissues derived from different organs." (PMID 37566748, 2023).